PRKCZ (protein kinase C zeta)
Description:
Calcium- and diacylglycerol-independent serine/threonine-protein kinase that functions in phosphatidylinositol 3-kinase (PI3K) pathway and mitogen-activated protein (MAP) kinase cascade, and is involved in NF-kappa-B activation, mitogenic signaling, cell proliferation, cell polarity, inflammatory response and maintenance of long-term potentiation (LTP). Upon lipopolysaccharide (LPS) treatment in macrophages, or following mitogenic stimuli, functions downstream of PI3K to activate MAP2K1/MEK1-MAPK1/ERK2 signaling cascade independently of RAF1 activation. Required for insulin-dependent activation of AKT3, but may function as an adapter rather than a direct activator. Upon insulin treatment may act as a downstream effector of PI3K and contribute to the activation of translocation of the glucose transporter SLC2A4/GLUT4 and subsequent glucose transport in adipocytes. In EGF-induced cells, binds and activates MAP2K5/MEK5-MAPK7/ERK5 independently of its kinase activity and can activate JUN promoter through MEF2C. Through binding with SQSTM1/p62, functions in interleukin-1 signaling and activation of NF-kappa-B with the specific adapters RIPK1 and TRAF6. Participates in TNF-dependent transactivation of NF-kappa-B by phosphorylating and activating IKBKB kinase, which in turn leads to the degradation of NF-kappa-B inhibitors. In migrating astrocytes, forms a cytoplasmic complex with PARD6A and is recruited by CDC42 to function in the establishment of cell polarity along with the microtubule motor and dynein. In association with FEZ1, stimulates neuronal differentiation in PC12 cells. In the inflammatory response, is required for the T-helper 2 (Th2) differentiation process, including interleukin production, efficient activation of JAK1 and the subsequent phosphorylation and nuclear translocation of STAT6. May be involved in development of allergic airway inflammation (asthma), a process dependent on Th2 immune response. In the NF-kappa-B-mediated inflammatory response, can relieve SETD6-dependent repression of NF-kappa-B target genes by phosphorylating the RELA subunit at 'Ser-311'. Phosphorylates VAMP2 in vitro. Phosphorylates and activates LRRK1, which phosphorylates RAB proteins involved in intracellular trafficking. [Isoform 2]: Involved in late synaptic long term potention phase in CA1 hippocampal cells and long term memory maintenance.
Synonyms: PKC2; PKC-ZETA
Tractability: Small molecule: an approved drug acts on it; a high-quality ligand is known; it belongs to a druggable protein family. Antibody: UniProt places it where antibodies can reach, with high confidence; its Gene Ontology location is reachable by antibodies, with high confidence. PROTAC: a small molecule that binds it is known.
Target class: AGC protein kinase PKC iota subfamily; AGC protein kinase group; Protein Kinase; AGC protein kinase PKC family; Kinase; Enzyme
Chemical probes: CHEMBL2393448, Y-9680
Gene: Protein-coding gene on chromosome 1 (2,050,411 to 2,185,395, forward strand). Ensembl gene ENSG00000067606.
Subcellular location: Cytoplasm; Endosome; Cell junction; Membrane; Cytoplasm (Isoform 2)
Subcellular location (Human Protein Atlas): Cytosol; Basal body; End piece; Flagellar centriole; Mid piece; Plasma membrane
Pathways (Reactome):
Signal Transduction: Estrogen-stimulated signaling through PRKCZ; RHO GTPases Activate NADPH Oxidases; TGF-beta receptor signaling in EMT (epithelial to mesenchymal transition); VEGFR2 mediated cell proliferation
Hemostasis: GPVI-mediated activation cascade
Gene Ontology:
Molecular function: calcium,diacylglycerol-dependent serine/threonine kinase activity; insulin receptor substrate binding; protein binding; protein kinase activity; protein serine kinase activity; protein serine/threonine kinase activity; diacylglycerol-dependent serine/threonine kinase activity; ATP binding
Biological process: negative regulation of insulin receptor signaling pathway; negative regulation of protein-containing complex assembly; positive regulation of ERK1 and ERK2 cascade; protein phosphorylation; cellular response to insulin stimulus; establishment of cell polarity; intracellular signal transduction; long-term synaptic potentiation; negative regulation of apoptotic process; positive regulation of excitatory postsynaptic potential; positive regulation of insulin receptor signaling pathway; positive regulation of interleukin-10 production; positive regulation of interleukin-13 production; positive regulation of interleukin-4 production; positive regulation of interleukin-5 production; positive regulation of T-helper 2 cell cytokine production; positive regulation of T-helper 2 cell differentiation; protein localization to plasma membrane; signal transduction
Cellular component: anchoring junction; cell-cell junction; cytoplasm; cytosol; endosome; extracellular exosome; vesicle; cell junction; membrane; plasma membrane; tight junction; apical cortex; apical plasma membrane; axon hillock; bicellular tight junction; cell cortex; microtubule organizing center; myelin sheath abaxonal region; nuclear envelope; nuclear matrix; nucleus
Genetic constraint (gnomAD): Loss-of-function variants: 33 observed, 76.62 expected, observed/expected ratio (o/e) 0.43, 90% interval 0.32 to 0.58. The upper end of that interval is the gene's LOEUF score, 0.58, which puts it in group 2 of 6, group 1 being the genes least tolerant of losing a copy. Missense variants: 576 observed, 803.83 expected, observed/expected ratio (o/e) 0.72, 90% interval 0.67 to 0.77. Synonymous variants: 342 observed, 325.62 expected, observed/expected ratio (o/e) 1.05, 90% interval 0.96 to 1.15.
Homologues: Orthologues: macaque PRKCZ (99% identical), rat Prkcz (96% identical), mouse Prkcz (96% identical), dog PRKCZ (95% identical), guinea pig PRKCZ (94% identical), pig PRKCZ (92% identical), tropical clawed frog prkcz (83% identical), zebrafish prkcz (82% identical), Drosophila melanogaster Pkcdelta (34% identical), Caenorhabditis elegans tpa-1 (34% identical), Drosophila melanogaster Pkc53E (34% identical), Caenorhabditis elegans pkc-2 (32% identical), and 3 more. Paralogues in human: PRKCI (71% identical), PRKCE (41% identical), PRKCH (38% identical), PRKCB (36% identical), PRKCA (36% identical), PRKCG (34% identical), PKN2 (32% identical), PKN1 (30% identical), PKN3 (30% identical).
Diseases named in the same sentence as PRKCZ in open-access papers:
PRKCZ is named in the same sentence as 85 diseases in open-access papers, as found by Europe PMC text mining. Sharing a sentence is not in itself a finding about the gene and the disease. The quoted sentences say what the papers report.
breast carcinoma (8 papers, 2015 to 2023). "In contrast to our findings that untransformed MECs use Rictor to activate PKC-alpha and Rac1-mediated invasion, breast cancer cells used Rictor to drive motility through protein kinase C-zeta (PKC-zeta;), integrin-linked kinase (ILK;) and Akt." (PMID 26132202, 2015). "Mutation of PIK3R5 and other genes (i.e. PRKCZ, PTEN, RHEB and RPS6KB1) have altered PI3K signaling pathway, which is the central pathway for both colorectal and breast cancers." (PMID 27161113, 2016). "Aberrant expression of PRKCZ is an example of such alteration, as its role in migration has previously been demonstrated in breast cancer, head and neck tumour cells, and pancreatic cancer." (PMID 25874946, 2015). "The mRNA relative expression of PRKCZ was significantly higher than PRKCI in breast cancer cells, including 4T1 cells and MDA-MB-231 cells, which indicating PKC-ζ may be activated by superoxide more easily than PKC-ι." (PMID 37029374, 2023). "We found that the vast majority of IGF regulators were upregulated in various cancers, such as HRAS and YWHAZ in lung squamous cell carcinoma (LUSC), SHC1 in kidney cancer, PRKCZ in bladder cancer (BLCA) and in breast cancer (BRCA), and NCK2 in cholangiocarcinoma (CHOL)." (PMID 35935986, 2022).
Insulin resistance (7 papers, 2009 to 2025). Increased resistance towards insulin, that is, diminished effectiveness of insulin in reducing blood glucose levels. "Recuperated animals expressed decreased levels of many insulin signalling proteins including PI3 kinase subunits p85α (P = 0.018), p110β (P = 0.048) and protein kinase C zeta (P = 0.006) which may predispose these animals to insulin resistance." (PMID 19308256, 2009). "Protein kinase C/zeta (PRKCZ) is a novel biomarker for the development of insulin resistance." (PMID 30678306, 2019). "In addition, PRKCD is implicated in intracellular accumulation of ROS, leading to oxidative stress and insulin resistance in adipose tissues, while there is defective PRKCZ activity and glucose uptake (insulin resistance) in muscle and adipose tissues in T2DM cases." (PMID 40572705, 2025). "The samples from the carotid sheath showed an enriched expression of genes described to play a role in insulin resistance (PPP1R3E, PRKCQ, PRKCZ, CPT1B, MGEA5, RPS6KB2, OGT; KEGG_PATHWAY hsa04931:Insulin resistance)." (PMID 32661330, 2020). "Methylation of PRKCZ in the underfed group negatively correlated with INSR and IRS1 expression, and positively with CRP, showing a relationship between methylation and inflammatory and insulin resistance markers." (PMID 38256201, 2024).
Obesity (7 papers, 2015 to 2025). Accumulation of substantial excess body fat. "For example, NO2 and PM can affect the methylation of the protein kinase C zeta (PRKCZ) gene, which is involved in insulin signaling and is associated with obesity and fasting blood glucose levels." (PMID 37999546, 2023). "NO2 and PM also affect DNA methylation at the protein kinase C zeta gene (PRKCZ), at which differential methylation is also associated with obesity and fasting glucose levels." (PMID 35773726, 2022). "When we investigated the list of 162 DMRs mapping to annotated loci in further detail we observed other genes with known and potential roles in obesity and related traits (such as PRKCZ, NDUFS2, GATA2, FOXP2, ANGPT2, NCOR2, CPT1B, PTPN6)." (PMID 25651499, 2015). "At least 4/15 genes containing ≥6 differentially methylated CpG sites had a potential role in obesity and/or related traits (PRKCZ, PRDM16, FOXP2, THBS1)." (PMID 25651499, 2015).
Type 2 diabetes (7 papers, 2011 to 2022). "PRKCZ hypermethylation plays a vital role in several diseases, such as type 2 diabetes mellitus, CTCF deletion syndrome, and postmenopausal osteoporosis." (PMID 36077689, 2022). "From those genes, we manifested that the expression of three critical genes in the type II diabetes pathway was altered, including HK2 (down-regulated), PRKCZ (up-regulated) and SOCS3 (down-regulated)." (PMID 35606885, 2022). "It was also suggested that the PRKCZ gene was the hypermethylated gene of type 2 diabetes mellitus (T2DM) and the hypermethylation PRKCZ gene may be involved in the pathogenesis of T2DM." (PMID 35174173, 2021).
pancreatic cancer (6 papers, 2010 to 2017). "PRKCZ has been shown to correlate with metastasis potential in pancreatic cancer cells, and PLCG1 and PIK3CD have been demonstrated to be associated with invasiveness of several cancer cells." (PMID 23451142, 2013). "We have previously demonstrated the specific involvement of the PRKCZ isoenzyme in the regulation of pancreatic cancer cell motility." (PMID 20236512, 2010). "In this study, we investigate the role of protein kinase C zeta (PKCζ) in pancreatic cancer cells." (PMID 24015205, 2013).
diabetes (5 papers, 2013 to 2022). "In recent years, there has been significant research on the relationship between protein kinase Cζ isoforms (protein kinase C epsilon zeta, PRKCZ, or PKCζ) and diabetes." (PMID 23671888, 2013).
prostate carcinoma (4 papers, 2015 to 2024). A carcinoma that arises from epithelial cells of the prostate gland. "PRKCZ has previously been implicated to be involved in various cancer cell types, including glioblastoma, prostate cancer, squamous cell carcinomas of the head and neck, squamous cervical cancer and soft tissue sarcomas." (PMID 25874946, 2015). "They suggested that PRKCZ acts as a potential tumor suppressor in intestinal tumors, prostate cancer, and lung cancer via involvement in metabolism reprogramming, suppressing the polarization of macrophages to the M2 phenotype, and inhibiting EMT." (PMID 36077689, 2022). "After knocking down PRKCZ expression via siRNA, prostate cancer cells presented impaired proliferation, migration, and tumorigenesis, which resulted from changed voltage-gated K+ channel activity." (PMID 36077689, 2022). "The study validated two key PPARγ target genes, PRKCZ and PGK1, which were repressed upon PPARγ activation by its natural ligand, 15d-PGJ2, in three prostate cancer cell lines." (PMID 39065726, 2024).
bladder cancer (3 papers, 2021 to 2024). "Through univariate and multivariate Cox proportional hazard regression analysis, we concluded that FASLG and PRKCZ can be used as prognostic biomarkers for bladder cancer." (PMID 35174173, 2021). "In our study, the analysis of genes PRKCZ, PTK2, and IL-18 underscores their significant roles in bladder cancer carcinogenesis, progression, and survival outcomes." (PMID 39064604, 2024).
cardiomyopathy (3 papers, 2014 to 2023). A disease of the heart muscle or myocardium proper. "In the literature from 22 to 27% of patients presented cardiomyopathy and two critical regions for cardiomyopathy have been described one of which includes PRKCZ, SKI, and PRDM16." (PMID 36369750, 2023).
bipolar disorder (2 papers, 2015 to 2020). A disorder of the brain that causes unusual shifts in mood, energy, activity levels and the ability to carry out day-to-day tasks. "The PRKCZ gene has also been linked to development of bipolar disorder in line with the increased risk of psychiatric illness such as bipolar disorder in males compared to females." (PMID 26419829, 2015). "Several genes were validated in APA sperm that were associated with autism spectrum disorder (CACNA1H, CNTNAP2, GRIN1, SHANK2, SHANK3, ZNF804A), schizophrenia (TCF3, ZNF804A), and bipolar disorder (COMT, DRD4, GRIN1, MBP, PRKCZ, SHANK2, TRPM2, ZNF804A), and in APA blastocysts (CACNA1H)." (PMID 32610362, 2020).
hepatocellular carcinoma (2 papers, 2022 to 2023). A malignant tumor that arises from hepatocytes. "In COX-2-induced hepatocellular carcinoma, PRKCZ was hypermethylated and associated with reduced gene expression." (PMID 36077689, 2022). "However, the relationship between PRKCZ methylation and the biological behaviors of hepatocellular carcinoma cells has not been thoroughly studied." (PMID 36077689, 2022). "screened potential autoantibody-based markers for hepatocellular carcinoma (HCC) and found that the AUC of an immunodiagnostic model including 6 TAAbs (RAD23A, CAST, RUNX1T1, PAIP1, SARS, PRKCZ) were 0.835 and 0.788 in the training and validation sets, respectively." (PMID 37251926, 2023).
memory impairment (2 papers, 2012 to 2023). "PKMzeta, an N-terminal truncated form of PRKCZ, can accumulate in NFTs and disrupt glutamatergic synaptic transmission, leading to memory impairment in AD." (PMID 22815752, 2012).
multiple sclerosis (2 papers, 2017 to 2020). A progressive autoimmune disorder affecting the central nervous system resulting in demyelination. "In addition, PRKCZ, though not included in our bisulfite pyrosequencing validation analysis, was reported before to be associated with the metabolism of serum vitamin D and relapse in multiple sclerosis." (PMID 29387007, 2017).
osteoporosis (2 papers, 2020 to 2025). A condition of reduced bone mass, with decreased cortical thickness and a decrease in the number and size of the trabeculae of cancellous bone (but normal chemical composition), resulting in increased fracture incidence. "We identify Thyroid Hormone Receptor Beta (Thrb) and Protein Kinase C Zeta (Prkcz) as potential therapeutic targets for the treatment of osteoporosis." (PMID 40204733, 2025). "Our result indicated that PRKCZ, GAN11 and COL4A1 may be associated with the development of osteoporosis in postmenopausal women." (PMID 32496000, 2020).
ovarian carcinoma (2 papers, 2015 to 2019). A malignant neoplasm originating from the surface ovarian epithelium. "For instance, genes PRKCQ and PRKCZ are members of the protein kinase family and PRKCZ is often involved in cell survival and cell migration in different cancers such as ovarian cancer." (PMID 31888617, 2019). "Our current study revealed that PRKCZ also plays a role in proliferation in a subset of ovarian cancer cell lines, as it was observed that it affects cell viability in SKOV3 cells, but not OVCAR3 cells." (PMID 25874946, 2015). "Our observation suggests that the endogenous level of PRKCZ is sufficient for cell motility in this particular ovarian cancer cell line." (PMID 25874946, 2015). "Herein, we observe a significant increase in cell survival upon PRKCZ over-expression in SKOV3 ovarian cancer cells; additionally, when the cells are treated with small interference RNA (siRNA) targeting PRKCZ, the motility of SKOV3 cells decreased." (PMID 25874946, 2015). "Comparing migration of parental cell lines and PRKCZ-expressing counterparts indicated that over-expressing PRKCZ alone is not sufficient to exert increased migratory properties in the two ovarian cancer cell lines tested." (PMID 25874946, 2015). "Our data indicate that over-expressing PRKCZ in certain ovarian cancer cell lines can alter the expression of IGF1R, and the type of expression alteration is cell-line dependent." (PMID 25874946, 2015). "The results from our study suggest the potential roles of PRKCZ in ovarian cancer development; however, further investigations using an animal model are needed to elucidate the roles of PRKCZ and its molecular partners in ovarian cancer." (PMID 25874946, 2015). "The aim of this study was to investigate the potential roles of Protein Kinase C Zeta (PRKCZ) in ovarian cancer." (PMID 25874946, 2015). "In the present study, we aimed to determine if alteration in PRKCZ expression can drive such processes in ovarian cancer, including cell viability, proliferation, and cell migration." (PMID 25874946, 2015). "To address the potential roles of PRKCZ in ovarian tumourigenesis, including cell viability, proliferation, cell migration, as well as relevant downstream signalling pathways, we performed several in vitro functional assays using ovarian cancer cells." (PMID 25874946, 2015). "In the present study, we tested the hypothesis that PRKCZ plays a role in ovarian cancer cell viability, proliferation and migration." (PMID 25874946, 2015). "Based on these observations, we propose the following model by which PRKCZ may participate during tumour progression in a subset of ovarian cancer." (PMID 25874946, 2015). "Our data further illustrate that up-regulation of PRKCZ leads to expression alterations of IGF1R and ITGB3 in SKOV3 and OVCAR3 cell lines, suggesting that PRKCZ may participate in ovarian cancer progression by modulating the expression of other important signalling molecules." (PMID 25874946, 2015). "Given that PRKCZ expression correlates with the expression of both IGF1R and ITGB3, we further examined if alteration of these genes can affect the migration phenotype of ovarian cancer cells that over-express PRKCZ." (PMID 25874946, 2015). "Interestingly, our assessment of ITGB3 expression in PRKCZ-expressing SKOV3 and OVCAR3 ovarian cancer cells showed that ITGB3 is down-regulated in the presence of PRKCZ, as its gene and protein expressions were both decreased compared to controls." (PMID 25874946, 2015). "In addition to PRKCZ, it is also important to note the potential roles of PRKCI (protein kinase C iota) in ovarian cancer." (PMID 25874946, 2015). "Based on our observations that both ITGB3 mRNA and protein levels are decreased in PRKCZ-expressing cells in two ovarian cancer cell lines (SKOV3 and OVCAR3), we sought to identify potential downstream players within this signalling pathway that may play role in ovarian cancer." (PMID 25874946, 2015).